ATRX (ATRX chromatin remodeler)
Diseases named in the same sentence as ATRX in open-access papers (continued):
Sharing a sentence is not in itself a finding about the gene and the disease.
ATRX syndrome (24 papers, 2008 to 2025). "Alpha-thalassemia X-linked intellectual disability syndrome (ATR-X syndrome) is a rare genetic disorder caused by mutations in the ATRX gene, typically affecting males and presenting with neurodevelopmental and systemic manifestations." (PMID 40896065, 2025). "ATRX syndrome is primarily caused by ATRX mutations and characterized by ATRX deletion or missense mutations." (PMID 39479502, 2024). "ATRX syndrome is closely related to mutations in ATRX, and its detection and risk of in carriers is particularly important because of its significant impact on child intelligence (León and Harley, 2021)." (PMID 39479502, 2024). "The majority of missense mutations leading to ATRX syndrome occur within the ADD domains in ATRX patients." (PMID 39479502, 2024). "Most ATRX syndrome mutations result in protein instability and reduced overall levels of ATRX protein." (PMID 35998910, 2022). "Both alpha-thalassemia x-linked intellectual disability syndrome (ATRX) gene mutation and MGMT promoter methylation occurred less frequently in cluster 3 than in other clusters." (PMID 36267281, 2022). "Mutations in the ATRX chromatin remodeler cause a severe neurodevelopmental disorder known as ATRX syndrome." (PMID 35998910, 2022). "Previous studies using ATRX syndrome patient cell lines show that while some ATRX missense mutations result in reduced protein levels, others do not significantly impact protein stability." (PMID 35998910, 2022). "XH2 was subsequently renamed ATRX, because of its causative role in the development of ATRX syndrome." (PMID 32218364, 2020). "The mutations in ATRX that cause ATRX syndrome are located in either the ATRXADD or the ATRXATP domain." (PMID 32218364, 2020). "Nevertheless, PDCLs preserved the main genomic aberrations found in patient tumors, including histone, ATRX (alpha-thalassemia/mental retardation syndrome X-linked) mutations, and CDKN2A (cyclin-dependent kinase inhibitor 2A) homozygous deletion." (PMID 31779235, 2019). "Germline mutations in ATRX have been reported as a cause of X-linked alpha thalassemia mental retardation syndrome (ATRX syndrome)." (PMID 30538672, 2018). "It has not escaped our attention that despite all the mutations identified in ATRX syndrome patients and, more recently, in distinct cancer types, few ATRX over-expression experiments mimicking such mutations have been published." (PMID 24834375, 2014). "ATRX is chromatin remodeling protein that is a SWI2/SNF2 DNA helicase ATPase that is the cause of ATRX syndrome." (PMID 20163734, 2010). "Moreover, ATRX mutation is associated with alpha thalassemia X-linked intellectual disability syndrome, often manifested as generalized cognitive impairment." (PMID 38315329, 2024). "ATRX syndrome is associated with the overexpression of ATRX in the nucleus." (PMID 39479502, 2024). "ATRX mutations not only cause ATRX syndrome but also influence development and promote cancer." (PMID 37190157, 2023). "ATRX is a chromatin remodeler, which is mutated in ATRX syndrome, a neurodevelopmental disorder." (PMID 35998910, 2022). "ATRX contains an ATPase/helicase domain that is often mutated in both ATRX syndrome and in cancers." (PMID 34162889, 2021). "Missense mutations in ATRX syndrome cluster in the PHD finger and helicase domains on the ATRX protein." (PMID 35998910, 2022). "Importantly, ATRX syndrome is attributed to recurrent substitutions in a highly conserved residue, residue 2,085, within the helicase domain of ATRX." (PMID 39479502, 2024). "ATRX syndrome manifests as multiple bodily system abnormalities, which are related to various factors, such as ATRX structural alterations, interacting proteins, and the regulation of gene expression." (PMID 39479502, 2024). "The ATRX variant c.21-1G>A was detected by an exome analysis of a patient with Cockayne syndrome without alpha thalassemia X-linked intellectual disability syndrome (ATR-XS)." (PMID 36104326, 2022).
ATRX syndrome (continued). "Our results indicate that the histone binding and chromatin remodeling functions of ATRX play non-redundant roles in neurodevelopment, and when mutated lead to ATRX syndrome through separate regulatory pathways." (PMID 35998910, 2022). "ATRX mutations in the PHD finger and the helicase domains cause ATRX syndrome." (PMID 35998910, 2022). "Mutations linked to the ATRX syndrome mostly cluster within the helicase and PHD domains of ATRX." (PMID 29034211, 2017). "Moreover, further studies will be required to determine whether the association of ATRX with the mammalian Y chromosome has a functional implication for the onset of gonadal dysgenesis and the abnormal male sexual differentiation phenotypes observed in human patients with ATRX syndrome." (PMID 18366812, 2008). "In addition, the role of ATRX in tumorigenesis and its mechanism is described to comprehend its role in normal biology and tumors and explore potential research directions in pathogenesis of ATRX syndrome and cancer." (PMID 39479502, 2024). "Although ATRX does not contain a canonical DNA methyltransferase motif, DNMT3B and ATRX share a closely related plant homeodomain (PHD)-like zinc finger domain and patients with ATRX syndrome exhibit alterations in DNA methylation at repetitive sequences." (PMID 20885787, 2010).
mental retardation syndrome X-linked (21 papers, 2012 to 2025). "The ATRX-related diseases have emerged as a prominent syndrome among the many X-linked intellectual disability syndromes." (PMID 35444965, 2022).
astrocytic tumor (20 papers, 2012 to 2025). A glial tumor of the brain or spinal cord showing astrocytic differentiation. "Since loss of ATRX is a distinguishing feature of astrocytic tumors, ATRX helps to better defining the symptomatic and structurally mixed group of AOA." (PMID 37675821, 2023). "In a prospective study conducted on a cohort of patients with astrocytic tumors (grade I-IV), those with a loss of ATRX expression had a better prognosis than those who retained ATRX expression and a co-occurring IDH mutation." (PMID 35626018, 2022). "One notable example in Group C was Patient 34 who appeared to have gained a mutation in ATRX, a key mutation involved in diagnosing astrocytic tumors." (PMID 32118206, 2020). "ATRX loss occurs almost exclusively in IDH mutant astrocytic tumors, and ATRX loss and 1p/19q codeletion are largely mutually exclusive." (PMID 27713914, 2016). "Patients with IDH1-R132H positive or ATRX loss astrocytic tumors had a longer progressive- free survival (p<0.0001, p=0.0044, respectively)." (PMID 27713914, 2016). "Decreased ATRX expression was associated with favorable survival of patients with astrocytic tumors (p = 2.15e–05)." (PMID 25971279, 2015). "This analysis revealed for the first time to our knowledge that ATRX mutations are frequent among grade II-III adult astrocytic tumors and are tightly associated with an ALT phenotype." (PMID 22869205, 2012). "Furthermore, loss of ATRX expression has been linked to extensive epigenomic alteration including CPG island hypermethylation observed in astrocytic tumors." (PMID 28293299, 2017). "In contrast with IDH mutations and ATRX loss being widely considered as key aberrations in the early stage of astrocytic tumors, higher Ki-67 expression may be the final event in the progression of these tumors." (PMID 27713914, 2016). "In current work, we aimed to study whether ATRX expression was associated with DNA methylation level in astrocytic tumors and in which cellular functions it participated." (PMID 25971279, 2015). "We conducted an extensive DNA methylation and mRNA expression profile study on a cohort of 82 patients with astrocytic tumors to study whether ATRX expression was associated with DNA methylation level in astrocytic tumors and in which cellular functions it participated." (PMID 25971279, 2015). "Anaplastic gliomas that are more accurately classified by ATRX deletion defines a subgroup of IDH mutant astrocytic tumors with a longer useful life." (PMID 37675821, 2023). "ATRX loss was also a favorable prognostic factor in patients with astrocytic tumors (Median PFS of ATRX loss=693 days, Median PFS of ATRX expression=459 days; p=0.0044)." (PMID 27713914, 2016). "We observed that astrocytic tumors with lower ATRX expression harbored higher DNA methylation level at chromatin end and astrocytic tumors with ATRX-low had distinct gene expression profile and DNA methylation profile compared with ATRX-high tumors." (PMID 25971279, 2015). "On the other hand, several clearly astrocytic tumors (with purely astrocytic morphology, ATRX loss and lack of TERT promoter mutation) were identified as 1p/19q co-deleted using Natté’s criteria." (PMID 29923492, 2018).
astrocytic tumor (continued). "We speculated that IDH1- R132H accompanied by ATRX or Ki-67 may represent a distinct biological process during the development of astrocytic tumors from the original tumor cells." (PMID 27713914, 2016). "We observed that ATRX-low astrocytic tumors harbored lower MGMT expression." (PMID 25971279, 2015). "Interestingly, we observed that astrocytic tumors with lower ATRX expression companied with MGMT (O6-methylguanine–DNA methyltransferase) hypermethylation and downregulation." (PMID 25971279, 2015). "In accord with previous reports, among the 41 tumor samples with IDH1-R132H positive, 34 lacked ATRX nuclear protein, while 53 samples of 74 astrocytic tumors with IDH1-R132H negative expressed ATRX, indicating a strong association between ATRX loss and IDH1-R132H (p<0.0001, Chi-Square test)." (PMID 27713914, 2016). "ATRX, IDH1/2, and Ki-67 collaboratively define three distinct subgroups of astrocytic tumors, offering a molecular classification that transcends the conventional WHO grading system." (PMID 40282990, 2025). "In astroglioma, IDH1R132H combined with ATRX knockout induces APBs, the primary sites of de novo telomere synthesis in ALT-positive cells." (PMID 39479502, 2024). "Then we evaluated the value of ATRX, IDH1- R132H and Ki-67 for predicting the progression of astrocytic tumors." (PMID 27713914, 2016). "In this study, we detected ATRX, IDH1-R132H and Ki-67 by immunohistochemistry and characterized three prognostic subgroups of astrocytic tumors (referred to as A1, A2 and A3)." (PMID 27713914, 2016). "We observed that astrocytic tumors with lower ATRX expression harbored higher DNA methylation level at chromatin end and astrocytic tumors with ATRX-low had distinct GEP and DNA methylation profile compared with ATRX-high tumors." (PMID 25971279, 2015).
melanoma (20 papers, 2019 to 2025). A malignant, usually aggressive tumor composed of atypical, neoplastic melanocytes. "In melanoma, early loss of miR-101-3p led to genomic instability, while its reexpression inhibited proliferation and induced apoptosis by targeting Lamin B1, ATRX, CASP3, and PARP." (PMID 40074445, 2025). "ATRX mutations are also described in other mucosal melanomas, including melanomas from gynecologic sites, the anorectal region, and the oral region." (PMID 37629169, 2023). "Whole-exome sequence analysis was also performed on the patient’s blood and melanoma, which showed a rarely-reported ATRX mutation." (PMID 35365243, 2022). "ATRX alterations or mutations are immunohistochemically expressed as protein loss, with recent studies highlighting the loss of protein immunoexpression during melanoma progression, thus making ATRX a valuable prognostic biomarker." (PMID 35334544, 2022). "Mutations in the ATRX gene, which is involved in chromatin remodeling, have been observed in mucosal melanomas previously." (PMID 33724703, 2021). "In mucosal-melanoma-inactivating ATRX mutations can be revealed using immunohistochemistry." (PMID 37629169, 2023). "Similarly, mutations in the components of the SWI/SNF chromatin remodeling complex, such as AT-rich interactive domain-containing protein 2 (ARID2) and ATRX Chromatin Remodeler (ATRX) have been identified in melanoma samples." (PMID 40554927, 2025). "The finding of ATRX mutations in melanoma originating from locations without sun exposure and the association with non-sun-exposed conjunctiva suggest that a (direct) relation between UV and ATRX is less likely." (PMID 37629169, 2023). "As most CM derive from PAM+, we compared primary acquired melanosis without atypia (PAM−) with PAM+ to determine whether ATRX loss is likely to be an early event in melanoma genesis." (PMID 37629169, 2023). "Moreover, ATRX is described to interact with EZH2, which has already been confirmed as a direct target of miR-101-3p in melanoma." (PMID 38431560, 2024). "Therefore, the expression of important proteins such as EZH2, ATRX, and LMNB1 can be maintained or adapted to keep and stabilize the increased proliferation rate of melanoma cells." (PMID 38431560, 2024). "However, equine melanomas from mucosal‐like or mucocutaneous sites showed a landscape of driver genes that was less populated than human mucosal melanoma, and there were fewer recurrently mutated genes in common with human mucosal melanoma, with no mutations found in SF3B1, ATRX or NF1." (PMID 32652526, 2020).
metastatic disease (19 papers, 2017 to 2026). "Remarkably, this ATRX copy number loss was the sole DNA alteration detected in the metastatic tumor, underscoring its potential as a driver of disease progression in this case." (PMID 41317331, 2026). "This mini-series supports prior studies showing aggressive/metastatic PCC in patients with somatic ATRX variants, as all developed widespread metastatic disease." (PMID 39351526, 2024). "This supposition is further supported by the finding that the majority of CM with metastatic disease revealed either ATRX loss or a TERT promoter mutation." (PMID 37629169, 2023). "Since most CMs with metastatic disease show either ATRX loss or a TERT promoter mutation, both alterations are suggestive of an association with adverse clinical behavior." (PMID 37629169, 2023). "Other recent studies have confirmed in a large series of PanNET patients that alternative lengthening of telomeres (ALT) and loss of DAXX/ATRX predict metastatic disease and poor survival in patients with PanNET." (PMID 29156578, 2017). "Recent studies indicate that loss of DAXX/ATRX expression and alternative lengthening of telomeres predict metastatic disease and poor survival in PanNET patients." (PMID 29156578, 2017). "According to these observations, it was concluded that ALT and DAXX/ATRX loss in PanNET was associated with reduced survival and seems to play an important role in driving metastatic disease." (PMID 29156578, 2017). "Additionally, a metastatic tumor (Case 24) exhibited heterozygous ATRX copy number loss despite preserved ATRX protein expression." (PMID 41317331, 2026). "Although we confirmed TERT/ATRX-alterations are associated with metastatic disease, the utility of these mutations as predictive biomarkers may be limited by the late timing of these events." (PMID 38978571, 2024). "Our data suggest that MEN1 alterations are an early event in tumorigenesis and that ATRX/DAXX variants may be later events in disease progression or occur more frequently in patients presenting with metastatic disease." (PMID 29212165, 2017). "Importantly, ATRX mutations were more common in pituitary carcinomas (28%) than in aggressive but non-metastatic tumors (13%), supporting the hypothesis that ATRX loss contributes to metastatic potential." (PMID 40364036, 2025). "Moreover, overexpression of miRNA-3653 may be associated with an increased risk of metastatic disease in pNENs, probably through the ATRX and ALT pathway interaction." (PMID 36556070, 2022). "In contrast, CNVs affecting genes involved in chromatin remodeling (e.g., SMARCB1 and ATRX) were exclusively identified in metastatic tumors." (PMID 41317331, 2026). "However, since all patients with ATRX variants presented with aggressive/metastatic disease despite initially presenting with PCC (low metastatic risk) and VHL or FH variants (low-moderate metastatic risk), we speculate, as others, that ATRX variants contribute to metastatic risk." (PMID 39351526, 2024). "ATRX expression was lost in both the primary and metastatic tumors from one silent corticotroph PitNET (patient 13)." (PMID 39388031, 2024). "Fifteen patients with conjunctival melanoma developed recurrent disease and eleven patients with conjunctival melanoma developed metastatic disease, with most of the cases with metastatic disease harboring either a TERT promoter mutation or ATRX loss." (PMID 37629169, 2023). "Patients with HRNB frequently present with widely metastatic disease, with tumors harboring recurrent genetic aberrations (MYCN amplification, TERT rearrangements, and ATRX mutations), which are mutually exclusive and capable of promoting TMM." (PMID 34439779, 2021). "In our study, we integrate large publicly available datasets of PANETs to show a remarkably conserved MEN1- and DAXX/ATRX-driven metastatic disease progression." (PMID 32345369, 2020).